NBPF20 (NBPF member 20)
Gene: Protein-coding gene on chromosome 1 (145,289,900 to 145,425,603, reverse strand). Ensembl gene ENSG00000162825.
Subcellular location: Cytoplasm
Subcellular location (Human Protein Atlas): Cytosol; Primary cilium; Cytokinetic bridge; End piece; Golgi apparatus; Microtubules; Mid piece; Principal piece; Vesicles
Genetic constraint (gnomAD): Loss-of-function variants: 58 observed, 40.66 expected, observed/expected ratio (o/e) 1.43, 90% interval 1.15 to 1.77. The synonymous counts are far from expectation, so gnomAD's model fits this gene poorly and the ratio says little. Missense variants: 629 observed, 390.04 expected, observed/expected ratio (o/e) 1.61, 90% interval 1.51 to 1.72. Synonymous variants: 234 observed, 145.58 expected, observed/expected ratio (o/e) 1.61, 90% interval 1.44 to 1.79.
Homologues: Paralogues in human: NBPF19 (67% identical), NBPF10 (61% identical), NBPF14 (47% identical), NBPF26 (20% identical), NBPF12 (16% identical), NBPF9 (15% identical), NBPF8 (11% identical), NBPF15 (11% identical), NBPF1 (10% identical), NBPF11 (9% identical), NBPF3 (8% identical), NBPF4 (5% identical), and 1 more.
Diseases named in the same sentence as NBPF20 in open-access papers:
NBPF20 is named in the same sentence as 7 diseases in open-access papers, as found by Europe PMC text mining. Sharing a sentence is not in itself a finding about the gene and the disease. The quoted sentences say what the papers report.
cervical cancer (1 paper, 2021). A primary or metastatic malignant neoplasm involving the cervix. "Previous studies have suggested the active role of NBPF20 in gene fusion in cervical cancer patients." (PMID 34368157, 2021).
diabetes (1 paper, 2023). "A direct relationship between NBPF Member 20 and pathogenesis of diabetes has not yet been reported; however, hypomethylation in the diabetic group through EWAS analysis of cg26823705 located within NBPF20 has been reported, which is consistent with our study." (PMID 38137029, 2023).
scoliosis (1 paper, 2021). A congenital or acquired spinal deformity characterized by lateral curvature of the spine. "Although the function of NBPF20 is unknown, it locates at chromosome 1q21.1, which microdeletion is associated with a variety of phenotypes including skeletal malformations such as scoliosis." (PMID 34440387, 2021). "Some candidates, such as DHX40, NBPF20, RASA2, and MYSM1, have been found to be associated with syndromes with scoliosis or implicated in bone/spine development." (PMID 34440387, 2021).
skin cancer (1 paper, 2021). "Highest frequencies of individual somatic variants in the TLSs of NBPF20 and CHCHD2 reached 10.1% among LAML and 8.1% among skin cancer patients, respectively." (PMID 34072580, 2021).
trigonocephaly (1 paper, 2017). "Likewise, none of the genes duplicated in patient 6 (NBPF20, GPR89A, PDZK1, CD160, RNF115) are known to cause trigonocephaly." (PMID 28724436, 2017).
tumours (1 paper, 2021). "Three more variants in KRTAP4-11, NBPF20 and LILRB3 were found in four primary tumour samples, each from patients without recurrence, while being absent in all primary tumours of patients with recurrences and the local/distant relapses." (PMID 35008243, 2021).
NBPF20 also shares sentences with these, for which no sentence is quoted: neuroblastoma (1 paper).